CXCL9 (C-X-C motif chemokine ligand 9)
Diseases named in the same sentence as CXCL9 in open-access papers (continued):
Sharing a sentence is not in itself a finding about the gene and the disease.
COVID-19 (continued). "Findings from mouse models, cellular systems, and samples from patients with SARS-CoV-2-induced COVID-19 have shown massive generation of C5a, CCL chemokines (e.g., CCL2, CCL3, and CCL5), CXCL chemokines (e.g., CXCL9 and CXCL10), and growth factors, i.e., TGFβ, GCSF, GMCSF, VEGF, FGF, and PDGF." (PMID 36430817, 2022). "Furthermore, Ruxolitinib, a JAK1/JAK2 inhibitor acting downstream of JAK-dependent chemokines/cytokines such as IFN-γ, IL-1β, IL-6, TNF, G-CSF, CXCL9, and CXCL10, has shown promising results in treating COVID-19." (PMID 35269470, 2022). "While baseline secretion of proinflammatory cytokines was massively elevated, whole blood from COVID-19 patients elicited diminished release of T-cellular (e.g., IFN-γ, IL-2) and innate immune cell-derived (e.g., CXCL9, CXCL10) cytokines in response to A. fumigatus and R. arrhizus antigens." (PMID 36052094, 2022). "Severe COVID-19 sufferers demonstrated increased levels of non-classical monocytes, several plasma chemokines such as CXCL9 cytokines (IL-6 and IL-10), and ROS as opposed to mild COVID-19." (PMID 36016187, 2022). "To further evaluate this, we measured BAL CXCL9, CXCL 10, and CXCL 11 via cytometric bead immune assay in an expanded cohort of HCs (n = 29) and post-COVID-19 patients (n = 38), including those samples on which Olink data were generated plus additional samples." (PMID 35151371, 2022). "Analysis of this larger sample set revealed that CXCL10 and CXCL11, but not CXCL9, were significantly upregulated in post-COVID-19 BAL compared with HC BAL." (PMID 35151371, 2022). "Similarly, Th1-type chemokines, CXCL9 and CXCL10, were elevated in the patient with COVID-19 vaccine-related myopericarditis compared to healthy and vaccine controls." (PMID 35251049, 2022). "In addition to displaying correlations with immune cell frequencies in the airways, the chemokines CXCL9, CXCL10, and CXCL11, and their receptor, CXCR3, are all members of the red WGCNA module that characterized the post-COVID-19 airway." (PMID 35151371, 2022). "To investigate the role of cytokines and chemokines in the inflammatory status of COVID-19 and MIS-C, we measured plasma levels of IL-1ß, IL-2, IL-4, IL-5, IL-6, IL-10, TNF-α, IL-17A, IFN-α, IFN-γ, CXCL10/IP-10, CXCL8/IL-8, CXCL9/MIG, CCL5/RANTES, and CCL2/MCP1." (PMID 33841438, 2021). "The analysis of the plasmatic levels of inflammatory chemokines and cytokines in patients with COVID-19 and MIS-C showed higher levels of IL-6, CXCL8, CCL2/MCP-1, CXCL9/MIG, and CXCL10/IP-10 in MIS-C, whereas CCL5 levels were significantly higher in the COVID-19 group." (PMID 33841438, 2021). "Significantly elevated levels of the inflammatory cytokines TNF-α, IL-1, IL-6, IFN-λ3, IL-6, IP-10, and CXCL9 have been documented in severe COVID-19 compared to non-severe disease cases." (PMID 34399775, 2021). "IL-6, CXCL10, CXCL9, CCL2, IL1-Ra, IL-10, G-CSF and TNF-α were the cytokines with the highest contribution to dimension 2 in the PCA and were significantly increased in acute COVID-19 patients in comparison to HC." (PMID 34572439, 2021). "Severe COVID-19 in controls, but not SOT recipients, was associated with a marked increase in several canonical proinflammatory serum cytokines and chemokines (e.g., IL6, CCL7, and CXCL9)." (PMID 38196658, 2023). "CXCL9 was significantly expressed in critical COVID-19 patients, but not in other groups." (PMID 37310504, 2023). "While some genes involved in monocyte and lymphocyte migration and function were expressed in the COVID-19(+) TV group (CCL13, CCL8, and CCL20), a greater number of these genes were expressed in the COVID-19(-) PU control group (CCL19, CCL18, CXCL13, CCL4, CCL5, CXCL9)." (PMID 37026002, 2023). "MiRNAs that were downregulated in serum of COVID-19 patients mainly target genes promoting angiogenesis (e.g., VEGFA, ANGPT2, COL4A1, FGF2, ZEB1), apoptosis, autophagy, stress response (e.g., ATG12, ATG14, ATG2B, SOD2, TXNIP), and inflammation (e.g., CXCL9, CXCL10, IL1R1, TNF)." (PMID 36032130, 2022).
COVID-19 (continued). "Specifically, we found that the expression of genes encoding proinflammatory cytokines (IL12B, IL15, IL6, IL12A and IL1B) and chemokines (CXCL9, CXCL11 and CXCL10) was broadly increased in COVID-19 patients and speculate that other viral infections may also induce expression of these genes." (PMID 33780352, 2021). "Thus, adipose IRF5 transcripts in obesity correlate positively with TNF-α, IL-1β, IL-6, CXCL8/IL-8, CXCL9/MIG, CXCL10/IP10, CCL2/MCP1, CCL5, and CCL7/MCP3, all of which can be elevated in COVID-19 “cytokine storm”; positive correlations with IL-2 and IL-12 have been reported by the same group." (PMID 33936053, 2021). "Interestingly, OSM also binds to the OSM receptor, leading to the recruitment of JAKs and subsequent signal transduction and activation of STAT3; thus, we can hypothesize that both CXCL9 and OSM participate in the upregulation of PD-L1 through the STAT activation pathway in COVID-19 patients." (PMID 36428847, 2022). "Moreover, research data showed that inflammatory macrophages were shared and strikingly abundant in severe COVID-19 bronchoalveolar lavage samples and inflamed RA synovium, with an obvious arrangement of pro-inflammatory genes and interferon response genes such as CXCL10, CXCL9 and so on." (PMID 35464423, 2022). "As the known CXCR3 ligands, CXCL9, CXCL10, and CXCL11, are predominantly induced by IFNγ, the presence of this CXCR3-expressing CD11b+CD14+ monocyte subset may be mechanistically related to the synchronous increase in the IFNγ-producing CD4+ T cell subset in our convalescent COVID-19 cohort." (PMID 34113347, 2021). "We found that similar to monocytes CCR2 and CXCR3 were upregulated in DC3 of COVID-19 patients suggesting that DC3 together with monocytes may be recruited from the circulation to the infected lung in response to a gradient of CCL2 and CXCR3 ligands CXCL9/10/11." (PMID 34614036, 2021). "Another study showed that COVID-19 convalescents at 4 months post infection had higher levels of IFN-β, IFN-λ1, CXCL9, CXCL10, IL-8, and sTIM-3, regardless of symptoms, compared to uninfected controls." (PMID 37077911, 2023). "The ongoing inflammatory response after acute COVID-19 remission keeps the expression of proinflammatory cytokines such as IFN-β, IFN-λ1, IFN-γ, IL-2, IL-6, IL-17, CXCL8, CXCL9, and CXC10 upregulated, the activation of non-classical and intermediate monocytes, fibroblasts, and myeloid cells." (PMID 38097988, 2023). "Serum CXCL9, CXCL10, CXCL11, and CXCR3 levels were significantly higher in patients with severe COVID-19 than in those with non-severe COVID-19; were higher in both patient groups than in the control group; and were higher in patients who died than in those who survived." (PMID 37493737, 2023). "However, IL15, CXCL9 and IL12A levels were not significantly altered in KD or severe COVID-19 compared to FC or HC, respectively." (PMID 36159873, 2022).
breast cancer (110 papers, 2010 to 2026). A primary or metastatic malignant neoplasm involving the breast. "For instance, CXCR3-expressing breast cancer cells induced CXCL9/10 in lung metastasis-associated fibroblasts." (PMID 41129238, 2026). "In conclusion, by integrating single-cell RNA sequencing and bulk RNA-seq analysis, we demonstrate that CXCL9 + macrophages are associated with improved survival outcomes in breast cancer." (PMID 41325308, 2025). "In breast cancer, higher CXCL9 levels are generally linked to a favorable prognosis and enhanced antitumor immunity, including potential responsiveness to immunotherapies, particularly in ER-negative and triple-negative subtypes." (PMID 41462979, 2025). "In bulk RNA sequencing analysis, a risk score based on a gene signature comprising CXCL9 and T/NK cell-related genes showed good predictive power for breast cancer prognosis." (PMID 41325308, 2025). "Previous studies have demonstrated that high levels of CXCL9 mRNA are associated with prolonged survival in patients with breast cancer, particularly the TNBC subtype." (PMID 38957805, 2024). "Except CXCL10, high expression levels of CCL5, CCL19 and CXCL9 were significantly associated with better prognosis in breast cancer patients." (PMID 35359417, 2022). "Our study demonstrated that the level of CXCL9 was associated with the abundance of immune cell infiltration in breast cancer, which partially validated the expression of CXCL9 in this particular cancer being related to changes in immune function." (PMID 34527583, 2021). "In our studies, we found STAT‐5 and the resultant increased CXCR3 promoted the homing of PTPN2‐deficient CAR T cells to CXCL9/10‐expressing mammary tumours within 3 days of adoptive transfer." (PMID 31803974, 2020). "However, recent studies indicate that in ER-positive/HER2-negative breast cancer, higher CXCL9 expression is associated with a poorer prognosis." (PMID 40205245, 2025). "CXCL9 + macrophages could play a significant role in inhibiting breast cancer, and their infiltration into tumor tissues is associated with improved survival in breast cancer patients." (PMID 41325308, 2025). "For example, CXCL9 has been implicated in shaping the immune landscape of breast cancer." (PMID 41462979, 2025). "Furthermore, in a single-cell analysis of breast cancer, it was found that high expression of CXCL9/10 in M1 macrophages was linked to better response to immune checkpoint inhibitor therapy." (PMID 37540227, 2023). "Similarly, through the integrated analysis of multiple database platforms, our data showed that elevated CXCL9 levels were associated with favourable prognosis in breast cancer, especially in ER-positive BC." (PMID 34527583, 2021). "Moreover, CXCL9 overexpression in primary breast cancers is associated with increased T cell infiltration and enhanced chemotherapy responsiveness." (PMID 23408142, 2013). "For instance, in breast cancer patients, elevated serum levels of CXCL9 and CXCL10 are observed compared to healthy controls, and high levels of CXCL9 transcripts have been linked to better outcomes." (PMID 40362215, 2025). "Blocking the CXCL9/10-CXCR3 axis through CXCR3 inhibition has previously been proposed as a strategy for suppressing tumor metastasis to the lungs in breast cancer." (PMID 40447617, 2025). "For instance, while CXCL9 secreted by senescent endothelial cells accelerated breast cancer aggressiveness, macrophage-derived CXCL9 exhibited a positive correlation with T cells expansion in T-cell lymphomas." (PMID 40087771, 2025). "In breast cancer, Lut upregulates C-X-C motif chemokine ligand 9/10 (CXCL9/10) transcription via signal transducer and activator of transcription 1-interferon regulatory factor 1 (STAT1-IRF1) activation, enhancing CD8+ T cell recruitment to the TME." (PMID 41479912, 2025).
breast cancer (continued). "We conclude that decreased expression of CXCL9 (and potentially CXCL10) is associated with worse patient outcome and downregulation of CXCL9/10 with age is a feature of human HER2+ breast cancers." (PMID 41332581, 2025). "CXCL9, CXCL10, and CXCL11 have tumor-promoting abilities and have been associated with advanced human cancer, particularly in elderly breast cancer patients' progression and metastasis." (PMID 40584290, 2025). "The R o/e index indicated that M1 macrophages exhibited a stronger preference in normal samples, with an R o/e index of 4.29, while CXCL9 + macrophages showed a preference across all three breast cancer types." (PMID 41325308, 2025). "Kaplan-Meier survival curve analysis further confirmed that CXCL9 + macrophage infiltration was beneficial to the survival of breast cancer patients." (PMID 41325308, 2025). "The genes CXCL9, IL7R, CD79A, and CTSW were selected for their significant associations with overall survival (OS) and recurrence-free survival (RFS) in breast cancer patients." (PMID 40725191, 2025). "In the future, we plan to use this technique to explore the panoramic expression of important immune markers represented by CXCL9 in the immune microenvironment of breast cancer." (PMID 38957805, 2024). "Analyses among different breast cancer subtypes showed that CXCL9 mRNA levels in tumor tissues were much higher in the TNBC subtypes than in the luminal subtypes." (PMID 38957805, 2024). "For example, in breast cancer, the expression of C-X-C motif chemokine ligand 9 (CXCL9) correlates with an increase in the number of tumor-infiltrating lymphocytes, and high levels of CXCL9 suggest a prolonged survival of patients." (PMID 38367070, 2024). "While the dependency on IFN-ɣ for CXCL9/10 induction was previously known, our data show the cooperation between IFN-ɣ and TNF-α in promoting the secretion of CCL5 and CXCL9 from breast cancer cells." (PMID 38167224, 2024). "Previous studies have demonstrated that serum CXCL9 is upregulated in patients with breast cancer compared to healthy controls or benign breast tumors." (PMID 38957805, 2024). "Radiogenomic analysis identified 297 DEGs, including CXCL9, CCL18, and HLA-DPB1 which are known to be associated with breast cancer prognosis or angiogenesis." (PMID 38745321, 2024). "The expression of CXCR3 ligands (CXCL9/10/11) has been reported in cancer cells, and breast carcinoma cell lines." (PMID 38652012, 2024). "We also demonstrated that the inhibition of residual breast cancer growth by nsPEF was dependent on the CXCL9 axis." (PMID 37046739, 2023). "In conclusion, our work demonstrated that nsPEF effectively ablated the tumor, aroused an immune response, and inhibited residual breast cancer growth via CXCL9 axis dependence in mice." (PMID 37046739, 2023). "We found that the inhibition of residual breast cancer growth by nsPEF was dependent on the CXCL9 axis." (PMID 37046739, 2023). "Surprisingly, the CXCL9/10-binding chemokine receptor CXCR3 was specifically expressed in a small subset of breast cancer cells, exhibited tumor-initiating capacity when co-transplanted with fibroblasts, and had high JNK signaling Drives IL-1α/β expression." (PMID 36759842, 2023). "Blocking TIM3 receptor on cDC1 in breast cancer has shown an improved anti‐tumour response after chemotherapy by promoting intra‐tumour CD8+ T response mediated by CXCL9 expression." (PMID 38117000, 2023). "It was previously reported that in murine breast cancer models, CXCL9-expressing tumor cells reduced tumor growth and lung metastases through the recruitment of T cells." (PMID 35725915, 2022). "In this study, we focused on the potential of CXCL9 and TIS scores as immune signatures to identify patients at high risk for HER2-positive breast cancer, especially because both of these biomarkers are well known as predictors of ICI responses." (PMID 35954313, 2022).
breast cancer (continued). "We next confirmed that miR-155 overexpression upregulated Ccl5 and Cxcl9/10/11 expression in murine breast cancer cell lines using qPCR." (PMID 35925680, 2022). "In mouse mammary tumors treated with paclitaxel, aTim-3 mAbs act in Tim-3+ tumor-infiltrating cDCs to promote CXCL9-mediated recruitment of CD8+ T cells in a galectin-9–dependent fashion." (PMID 35316223, 2022). "SRC-3 inhibition by SI-2 or SRC-3 KD activates the Cxcl9/Cxcr3 axis in breast tumors and enhances the antitumor immune microenvironment to suppress breast cancer progression." (PMID 36316775, 2022). "Mechanistically, miR-155 overexpression in breast cancer cells upregulated their CXCL9/10/11 production, which was mediated by SOCS1 inhibition and increased phosphorylated STAT1 (p-STAT1)/p-STAT3 ratios." (PMID 35925680, 2022). "We observed that miR-155 dramatically upregulated CCL5 and CXCL9/10/11 expression in breast cancer cells." (PMID 35925680, 2022). "Future studies on the detailed molecular mechanism of CXCL9 in contributing to breast cancer immunity are warranted." (PMID 34527583, 2021). "Overall, our findings suggest the potential role of CXCL9 as a predictor of immune infiltration in breast cancer." (PMID 34527583, 2021). "The pan cancer analysis further confirmed and selected CXCL9 as the key innate immune checkpoint for breast cancer immunotherapy and identified three small molecular drugs for target CXCL9 through molecular docking analysis." (PMID 35052427, 2021). "We found that nine genes were differentially expressed in breast cancer versus normal tissues (CXCL9, 10, 11, and 13 were up-regulated, and CXCL1, 2, 3, 12, and 14 were downregulated)." (PMID 34439306, 2021). "The prognostic value of CXCL9 in breast cancer was evaluated using the Kaplan-Meier Plotter, Human Protein Atlas, UCSC Xena, TIMER and GEPIA2 databases." (PMID 34527583, 2021). "The results from the Kaplan-Meier Plotter demonstrated that low CXCL9 expression was correlated with shorter OS in breast cancer (HR=0.75, P<0.01), which was consistent with the results of OS (P<0.01), DFS (P<0.01), and PFS (P<0.01) in the UCSC Xena database." (PMID 34527583, 2021). "CXCL9 can be a tumor suppressor in breast cancer, non‐small cell lung carcinoma, and colorectal cancer." (PMID 35251116, 2021). "Correlation between CXCL9 expression and clinicopathological characteristics in patients with breast cancer." (PMID 34527583, 2021). "In Curtis’s breast database, CXCL9 was elevated 4.663-fold in breast cancer compared with normal tissues in a dataset with 2,136 samples (P<0.01)." (PMID 34527583, 2021). "According to the results, expression of CXCL9 was significantly correlated with immune cell infiltration in breast cancer patients and subtype patients, including basal-like, luminal-like and HER2 enriched." (PMID 35052427, 2021). "A similar result was found from a dataset from Gluck’s study, which showed that CXCL9 was increased 4.618-fold in breast cancer versus normal samples (P<0.01)." (PMID 34527583, 2021). "A previous study proved that CXCL9 was significantly involved in lymphocytic infiltration in breast cancer that responded to neoadjuvant therapy." (PMID 34527583, 2021). "Another dataset from The Cancer Genome Atlas (TCGA) demonstrated that CXCL9 transcripts were elevated 3.202-fold in breast cancer tissues compared with normal counterparts (P<0.01)." (PMID 34527583, 2021). "In the lung metastasis of breast cancer, IL-1α and IL-1β secreted by breast cancer cells induce the production of CXCL9 and CXCL10 in lung fibroblasts through NF-κB signal transduction, thus promoting the growth of lung metastasis." (PMID 33722297, 2021). "To determine the expression features of CXCL9 in breast cancer, we first compared the differences in CXCL9 expression between breast cancer and normal tissues through comprehensive analyses across multiple databases." (PMID 34527583, 2021).